TERT (telomerase reverse transcriptase)
Diseases named in the same sentence as TERT in open-access papers (continued):
Sharing a sentence is not in itself a finding about the gene and the disease.
colorectal cancer (continued). "In another recent study, a group showed that hsa_circ_0020397, a sponge of miR-138, promoted the expression of TERT and PD-L1, regulating the viability, apoptosis and invasion of colorectal cancer cells." (PMID 32122338, 2020). "TERT overexpression was found in most cancers and showed independent prognostic values in colorectal carcinoma." (PMID 32932803, 2020). "The human telomerase reverse transcriptase (hTERT or TERT) also plays an important role in colorectal cancer growth, conferring sustained cell proliferation and survival." (PMID 31614548, 2019). "Colorectal carcinoma displays a higher level of cell methylation within the TERT promoter and high degree tumours with TERTp methylation reveal high telomerase activity." (PMID 29751586, 2018). "We use data from a population-based study of colorectal cancer (CRC), where we have previously shown associations between TL and TERT and CRC, to test associations between TL and miRNA expression and TERT and miRNA expression." (PMID 27627813, 2016). "Our data, together with recent evidence for an association of the polymorphisms in the TERT-CLPTM1L locus with the risk of lung and colorectal cancer, suggest that the polymorphisms at this locus are potent genetic risk factors for the onset of NPC." (PMID 26621837, 2016). "Summary of miRNAs related to telomere length and TERT rs2736118 differentially expressed in colorectal cancer." (PMID 27627813, 2016). "Association studies on candidate gene strategy also reported that polymorphisms in the TERT-CLPTM1L locus were associated with serous ovarian, breast, endometrial, lung, and colorectal cancers." (PMID 26621837, 2016). "Notably, UrCAs tend to exhibit a lower frequency of TERT and RB1 alterations than BAC, whereas SMAD4 and GNAS mutations, which are frequently observed in colorectal cancer, are more commonly identified in UrCA." (PMID 39857670, 2025). "In colorectal cancer, miR-138 downregulation was observed in parallel to telomerase reverse transcriptase (TERT) upregulation, suggesting that miR-138-5p works at least partially through TERT downregulation, thus acting as tumor suppressor with the potential to inhibit telomerase expression." (PMID 35223454, 2021). "For example, telomerase reverse transcriptase (TERT) stimulates EMT in colorectal cancer through inhibition of E-cadherin expression by binding to ZEB1; histone H4K20-specific methyltransferase SET8 stimulates EMT in prostate cancer by inhibiting E-cadherin transcription through binding to ZEB1." (PMID 34210327, 2021). "Importantly, several studies have been demonstrated that circulating TERT mRNA is an independent prognostic marker in different types of tumors, including gastric, prostatic, lung, and colorectal cancers." (PMID 34746013, 2021). "Moreover, has_circ_0020397 was able to promote colorectal cancer cell growth and invasion by inducing TERT expression, through “sponging” TERT repressor miR-138." (PMID 32932969, 2020). "However, in other studies, telomerase had been identified as an independent prognostic marker for overall survival in colorectal cancer patients: patients with high TERT levels showed a significantly worse overall survival than those with lower TERT levels." (PMID 26913901, 2016). "In the miRNA panel, the studies reported that hsa-miR-18a-5p can significantly reduce the hazard of dying from colorectal cancer; hsa-miR-1182 can suppress the TERT gene expression level and might act as an effective target for gastric cancer treatment." (PMID 27271613, 2016). "Another circRNA, has_circ_0020397, was reported to be upregulated in colorectal cancer, promoting cell activity and invasion, but inhibiting apoptosis by acting as a miR-138 sponge to positively regulate its target genes telomerase reverse transcriptase (TERT) and PD-L1." (PMID 38177102, 2024). "TERT promoter mutations are not frequently found in leukemias and colorectal cancers." (PMID 26194807, 2015).
colorectal cancer (continued). "We demonstrate a use of this method in determining the methylation density of the promoter region of the tumor-related gene MLH1, TERT and MGMT in colorectal carcinoma patients." (PMID 18237388, 2008). "In order to validate the accuracy of the RMEAM approach, we analyzed the MLH1, TERT and MGMT promoter methylation density in 18 colorectal carcinoma patients." (PMID 18237388, 2008). "In colorectal cancer, TZAP expression showed a paradoxical effect on TERT expression." (PMID 36556980, 2022). "CircFMN2/miR-1182 may also regulate the progression of colorectal cancer by targeting CD44, GNG7, RB1, COL1A2, PLCB1, SLC17A7, and TERT." (PMID 34249673, 2021). "Interestingly, an oxaliplatin-resistant colorectal cancer cell line was shown to express increased TERT levels; this suggests that the input of another effective cytotoxic drug to manage chemoresistant tumor cells may facilitate anti-TERT immunity and possibly activate novel CD4 T cell clones." (PMID 32630460, 2020). "Nevertheless, the TERT mRNA level did not correlate with the number of TERT gene copies, as was also reported in colorectal cancer." (PMID 32722302, 2020). "In addition to HCC, TERT amplifications presented a substantial prevalence in lung adenocarcinoma (18%) and lung SCC (25%), colorectal carcinoma (48%), and cervical intraepithelial neoplasm (CIN) 2 and 3 (60% and 88%, respectively)." (PMID 29751586, 2018).
prostate carcinoma (55 papers, 2010 to 2025). A carcinoma that arises from epithelial cells of the prostate gland. "From the perspective of genetic mutations, prostate cancer generally lacks TERT promoter mutations, precluding their use as biomarkers." (PMID 39871386, 2025). "Mutation in telomerase reverse transcriptase (TERT) has been reportedly related to risks of prostate cancer (PCa)." (PMID 37174115, 2023). "The resultant synergistic effects of MYC/E2F1/TERT expression with the rs2853669 polymorphism further deteriorated the prognosis of prostate cancer." (PMID 37174115, 2023). "The primary objective of this study is to provide comparable and comprehensive evidence on TERT genetic variations in prostate cancer risk in two different ethnic populations." (PMID 37174115, 2023). "For instance, TERT promoter mutations increase the expression of the TERT gene, and gene polymorphisms are linked to prostate cancer invasion and a bad prognosis." (PMID 36157228, 2022). "Here, our association studies showed that the TERT promoter variant rs2853669 confers a risk of prostate cancer (PCa) in different ethnic groups." (PMID 34858826, 2021). "We examined the role of THOR (TERT Hypermethylated Oncological Region) as a diagnostic and prognostic biomarker in prostate cancer (PCa)." (PMID 27437772, 2016). "The SNPs in the TERT locus of 5p15 have been shown to affect prostate cancer risk by interfering with TERT expression." (PMID 27070714, 2016). "TheT allele of rs10069690 in TERT was associated with a decreased risk for prostate cancer, and it has also been associated with increasedregulated risks of breast and ovarian cancer." (PMID 27825130, 2016). "For prostate cancer, the association with the multi-SNP score became statistically significant after excluding TERT SNP rs2736100 and CTC1 SNP rs3027234." (PMID 26138067, 2015). "Similar results were obtained in prostate cancer cells transfected with anti-TERT siRNA, which caused significant inhibition of enzyme activity (up to 80 %)." (PMID 23677713, 2013). "In prostate cancer, fine-mapping of the original GWAS signal was performed, leading to the identification of four distinct TERT regions independently associated with prostate cancer risk." (PMID 23752272, 2013). "In addition to TERT, we found rare non-synonymous variants in three genes associated with decreased prostate cancer risk (ANO7, SPDL1 and AR), and three genes associated with increased risk (HOXB13, CHEK2 and BIK)." (PMID 39971927, 2025). "In contrast, in prostate cancer cells harboring mutated AR, androgen stimulates TERT expression, indicating that androgen in conjunction with a mutated AR may promote telomerase activity within prostate cancer cells." (PMID 39871386, 2025). "Interestingly, certain cancers, including lung and prostate cancer exhibit few TERT promoter mutations." (PMID 39871386, 2025). "Similarly, a TERT promoter variant enhances EMT in prostate cancer and promotes the development of castration-resistant prostate cancer." (PMID 38278800, 2024). "Kote-Jarai et al56 found that carriage of TERT rs2242652:A: was associated with a lower risk for developing prostate cancer and with increased TERT expression which has been reported to improves survival, in prostate cancer." (PMID 35788059, 2023). "It is well-documented that TERT was highly expressed in different cancers, with its promoter mutation being a possible marker for the poor diagnosis and prognosis of urothelial, bladder, thyroid papillary, prostate cancers, etc.." (PMID 31565554, 2019). "Furthermore, the inhibition of prostate cancer progression in TRAMP mice by CDDO-Me was associated with the inhibition of TERT phosphorylation and TERT regulatory proteins in the prostate." (PMID 23519253, 2012).
prostate carcinoma (continued). "Only for prostate cancer the association was stronger for rs10069690 than for VNTR6–1 and rs22942652, perhaps suggesting a more important role of decreased TERT expression due to intron 4 retention and INS1b-splicing in the molecular mechanism of this cancer." (PMID 39802763, 2024). "In prostate cancer cells, genistein reduces telomerase activity by inhibiting Akt, thereby dephosphorylating TERT." (PMID 38278800, 2024). "HDACi inhibited telomerase activity and downregulated TERT in childhood brain tumour cells, human normal TERT-immortalised fibroblasts, brain cancer cell lines, small-cell lung cancer lines and prostate cancer cells." (PMID 33802026, 2021). "For example, plasma ctRNA expression of the carcinoembryonic antigen has been used for diagnosis of early stage prostate cancer and plasma TERT mRNA levels have demonstrated to be predictive of response to chemoradiotherapy in rectal cancers." (PMID 33216826, 2020). "In pancreatic and prostate cancer, TERT activity has been detected, suggesting other means of telomerase activation." (PMID 32024817, 2020). "In prostate cancer cells, TERT is required for the symmetric CSC division by interacting with β-catenin and promoting β-catenin target expression." (PMID 31284662, 2019). "First, exclusion of the SNPs in the TERT and CTC1 regions from the SNP set used for overall prostate cancer resulted in a stronger, statistically significant association (OR = 1.45; 95% CI 1.18, 1.82; P = 7.9 × 10−4)." (PMID 26138067, 2015). "The model was able to identify prostate cancer associated SNPs that either map to a cancer specific genes such as CRR9, TERT, ATP2B2, ARL9, and AGBL4 and/or with regulatory effects." (PMID 24651484, 2014). "Nevertheless, the significant in vivo tumorigenicity of the cells and their unambiguous expression of TERT suggests that these CR-PrCa cells cultured from Stage-I prostate cancer represent an early manifestation of the carcinogenic process." (PMID 24086346, 2013). "Correspondingly, studies have demonstrated that antisense oligonucleotides against TERT resulted in inhibition of telomerase activity and induction of apoptosis in ovarian and prostate cancer cells." (PMID 23967300, 2013). "TERT expression in laser-enucleated tissues was tested for correlation with contractile smooth muscle receptors and the proliferation marker Ki67, and compared to tissues from radical prostatectomy for prostate cancer." (PMID 41379209, 2025). "Previous research identified four single nucleotide polymorphisms (SNPs) principally associated with circulating PSA levels rather than with prostate cancer risk (TERT rs2736098, FGFR2 rs10788160, TBX3 rs11067228, KLK3 rs17632542)." (PMID 26431041, 2015). "However, TERT promoter mutations have not been detected in prostate cancer, a cancer of low self-renewing tissue, suggesting that alterations within the core promoter of the TERT gene do not play an important role in prostate carcinogenesis." (PMID 27323951, 2016). "Some of the drugs that targeted these genes, such as AKT and TERT, were identified in GDSC as having more sensitivity in LNCaP than in the rest of the prostate cancer cell lines." (PMID 35164900, 2022). "By using the combination of tumor cytomorphology and ICC showing the presence of tumor-like markers, either EMT markers (epithelial+/vim+), PSMA, AMACR, or TERT, we found 50 PGCC from 22 prostate cancer patients, with an average number of 2.3 (range from 1 to 10)." (PMID 37444476, 2023).
prostate carcinoma (continued). "A total of 20 genes are involved in these intra-category multimorbid relationships and are mainly related to the human leukocyte antigen (HLA) complex (such as HLA-DQA1 and HLA-DRB1), histone clusters (such as HIST1H1B and HIST1H2AJ), and tumors (such as TERT and NOTCH4 for prostate cancer)." (PMID 34225788, 2021). "However, TERT, the catalytic protein component of the reverse transcriptase telomerase, itself does not suit as a prognostic marker for prostate cancer as it is rather low expressed." (PMID 35267575, 2022). "TERT expression has been shown, in tissue analyses, to be absent in patients with benign prostatic hyperplasia (BPH) but present in patients with prostatic intraepithelial neoplasia and prostate cancer." (PMID 37444476, 2023).
cutaneous melanoma (54 papers, 2013 to 2025). A primary melanoma arising from atypical melanocytes in the skin. "Japanese cutaneous melanomas harbored variants in TERT promoter regions and BRAF in some patients and were associated with sun exposure; however, the frequency was much lower than that in White patients." (PMID 39823560, 2025). "Previous studies have highlighted the significant role of TERT-p mutations in driving aggressive tumor behavior and poor prognosis across various cancers, including cutaneous melanoma." (PMID 40227833, 2025). "In the publicly available GENIE dataset, looking exclusively at cutaneous melanomas shows that the specific mutation rates within primary tumors were 55 % for TERT, 40 % for BRAF, 7.2 % for KIT, 2.5 % for NRAS, and 1.9 % for CDH1." (PMID 38158497, 2024). "Activating mutations in the proximal promoter of the TERT gene were first reported in cutaneous melanoma by two independent studies, and have subsequently be shown to occur more frequently than any other carcinogenic mutation in different tumour types." (PMID 38033865, 2023). "Recent studies have identified activating mutations in the promoter region of the ACD gene co-occurring with TERT promoter mutations in 5% of cutaneous melanoma." (PMID 38033865, 2023). "TERT promoter mutations, which cause an increased TERT expression, are detectable in 32% to 43% of primary conjunctival melanomas and 30% of primary cutaneous melanomas, correlating with metastatic diseases and a shorter survival." (PMID 37079315, 2023). "Addition of TERT promoter mutation targets in the custom panel was predicted to further increase coverage by ~15% in those cutaneous melanoma patients that are NRAS or BRAF WT." (PMID 35494035, 2022). "This study represents one of the first to successfully detect TERT promoter mutations in ctDNA from cutaneous melanoma patients using a targeted NGS panel." (PMID 35494035, 2022). "In cutaneous melanoma TERT promoter mutations commonly co-occur (80-90%) with NF1, BRAF or NRAS mutations, and TERT promoter mutations are also found in 15-60% of BRAF/NRAS/NF1 WT cutaneous melanoma background." (PMID 35494035, 2022). "TERT mutations have been seen in 85% of metastatic cutaneous melanoma tissues, and 33% of primary cutaneous melanomas, but are very rare in mucosal melanoma (8%)." (PMID 35163401, 2022). "TERT promoter mutations have also been described as an independent prognostic factor in cutaneous melanoma." (PMID 34071371, 2021). "TERT promoter mutations and TERT amplifications are common genetic events in the early stages of melanoma of the skin." (PMID 34350118, 2021). "In cutaneous melanoma, the presence of a TERT promoter mutation in addition to a BRAF mutation is associated with unfavorable clinicopathological characteristics, such as large tumor thickness and a high mitotic rate." (PMID 34071371, 2021). "Other mutations that are commonly found in cutaneous melanoma are TERT promoter mutations, suggesting that enhanced telomerase activity leads to proliferative immortality." (PMID 33256089, 2020). "The genetic spectrum of conjunctival melanoma, however, includes frequent mutations in the BRAF, NRAS and TERT promoter genes, which are found in cutaneous melanoma as well." (PMID 33396957, 2020). "TERT mutation occurs in up to 80% of cutaneous melanomas, which makes this gene extremely important to be part of the panel proposed." (PMID 33122747, 2020). "The occurrence of TERT promoter mutations in CjM is similar to cutaneous melanoma in which TERT mutations can be found in 64–68% of lesions, both in primary and metastases, and are associated with a shorter survival." (PMID 31683701, 2019). "Among the 115 samples analyzed by the TCGA consortium to establish the genomic classification of cutaneous melanoma, 65% were found with an activating mutation in TERT promoter, and 7% with a focal amplification of TERT locus." (PMID 29081790, 2017).